CDHR3 (cadherin related family member 3)
Diseases named in the same sentence as CDHR3 in open-access papers (continued):
Sharing a sentence is not in itself a finding about the gene and the disease.
asthma (continued). "This study identified novel associations of rs3847076 in CDHR3, as well as rs1892953, rs2508746 and rs12278256 in EMSY with adult asthma susceptibility in the Chinese Han population." (PMID 33213402, 2020). "A mutation (cysteine-to-tyrosine mutation at amino acid 529) in CDHR-3 enhances HRV-C binding and replication in vivo and has also been associated with increased susceptibility to wheezing and asthma illnesses." (PMID 31270180, 2019). "Applying this analysis to bronchial epithelial cells has revealed SNPs in TSLP, GSDMB, IL33, HLA-DQB1, C11orf30, DEXI, CDHR3, and ZBTB10 that affect asthma risk by allowing cis-regulation of its gene expression in an epithelial specific manner." (PMID 28583446, 2017). "Our data provide evidence for further disrupted function of CDHR3 in HRV-induced asthma exacerbation." (PMID 25706956, 2015). "Cadherin related family member 3 (CDHR3) was recently reported to be genetically associated with early childhood severe and recurrent asthma exacerbation, and highly expressed in airway epithelium." (PMID 25706956, 2015). "Kanazawa et al33 noted that the association between the CDHR3 variant and early-onset asthma was stronger in atopic individuals compared with nonatopic individuals." (PMID 40687950, 2025). "CDHR3 rs6967330 missense variant was previously associated with childhood-onset asthma, otitis media, and non-RSV bronchiolitis." (PMID 39299705, 2024). "CDHR3 and GSDMB loci were associated with asthma in previous studies and the pheWAS, and the GSDMB locus in the long arm of chromosome 17 (17q) is the strongest known asthma risk locus." (PMID 39299705, 2024). "In addition, various genes that are crucial in epithelial barrier homeostasis, like protocadherin 1 (PCDH1) and Cadherin-related family member 3 (CHHR3), have also been shown to be associated with asthma genetic studies." (PMID 36832296, 2023). "A single-nucleotide polymorphism in the CDHR3 rs6967330 locus has been linked to severe exacerbations of asthma and increased susceptibility to HRV-C infections in young children, possibly because of increased HRV-C binding and viral replication by the CDHR3 polymorphism." (PMID 38053068, 2023). "We investigated within- and between-phenotype differences compared with binary latent class analysis models and ascertained associations of these phenotypes with asthma and lung function and with polymorphisms in asthma loci 17q12–21 and CDHR3 (cadherin-related family member 3)." (PMID 35050846, 2022). "Importantly, functional validation of GWAS candidate asthma risk genes have uncovered key roles in HRV infection susceptibility (ORMDL3 and CDHR3) and TGFβ signalling (GSDMB, TGFBR1, and SMAD3)." (PMID 32887352, 2020). "Therefore, this study aimed to investigate the association of common variants in CDHR3 and EMSY with adult asthma in the Chinese population." (PMID 33213402, 2020). "CDHR3 (MIM 615610) encodes a transmembrane epithelial protein and was previously identified in GWAS for childhood ear infections and also for asthma exacerbations in children primarily due to viral respiratory infections." (PMID 32010199, 2019). "Genotyping of 41 chimpanzees and examination of 24 published chimpanzee genomes from subspecies across Africa showed universal homozygosity for the cadherin-related family member 3 CDHR3-Y529 allele, which increases risk for rhinovirus C infection and asthma in human children." (PMID 29350142, 2018). "A severe asthma GWAS identified a novel locus, CDHR3, that had not been observed using broader asthma definitions, in addition to the known asthma susceptibility loci GSDMB, IL33, and IL1RL1." (PMID 28774304, 2017). "Furthermore, functional disruption of CDHR3 has been reported in human rhinovirus-induced asthma exacerbation." (PMID 27658857, 2016). "Interestingly, genes previously associated with asthma, such as CCL5 (RANTES), CXCL10 (IP10), LGALS9, CX3CL1, C5AR1, and CDHR3 fall into these three different groups." (PMID 25706956, 2015).
asthma (continued). "The rs6967330 variant in cadherin-related family member 3 (CDHR3), which encodes a receptor for human rhinovirus C, was also analyzed, because studies on CDHR3 in adults are limited, despite its identification as a risk factor for asthma exacerbation in children similarly to GSDMB/ORMDL3." (PMID 40687950, 2025). "This CDHR3 allele has not yet been associated with canonical features of airway remodeling but viral susceptibility and increased asthma risk may play a role in the predisposition to remodeling features." (PMID 37773065, 2023). "The CDHR3 rs3847076 allele A and EMSY rs1892953 genotype GG may increase the risk of asthma." (PMID 33213402, 2020). "Secondly, the genotypes of other asthma genes were not determined in our cohort, so we were unable to examine any gene-gene interaction outside the CDHR3 locus." (PMID 37750685, 2023). "Forno and coworkers found an epigenetic prediction model based on DNA methylation of CDHR3 and other asthma genes to distinguish between atopic and non-atopic phenotypes in school-age asthmatic children." (PMID 37750685, 2023). "Our observations suggest that CDHR3 and EMSY may play important roles in the pathogenesis of asthma in Chinese individuals." (PMID 33213402, 2020). "Additionally, genetic variants in genomic region 17q21 and CDHR3 showed suggestive associations with non-RSV LRI phenotypes and later asthma." (PMID 39299705, 2024). "However because CDHR3 was identified in a GWAS for asthma, this gene was not included in overlaps between OM and Lower airway." (PMID 32010199, 2019). "We examined CDHR3 protein expression in bronchial epithelial cells, and we demonstrated that expression was localized to the apical surface of columnar epithelial cells and was increased in HDM sensitized atopics with asthma compared to nonatopic controls." (PMID 29367592, 2018).
childhood asthma (7 papers, 2016 to 2023). "Previous studies have shown that allele A at rs6967330 in CDHR3 is associated with an increased risk and increased severity of childhood asthma." (PMID 36967681, 2023). "One genome-wide association study (GWAS) of a Danish population identified Cadherin related family member 3 (CDHR3), which is highly expressed in human airway epithelium, as a susceptibility locus for childhood asthma with severe exacerbations." (PMID 33213402, 2020). "CDHR3 genotype was initially linked to the risk of childhood asthma with acute severe exacerbations, and subsequent studies showed that transfection of HeLa cells with CDHR3 rendered the cells permissive for RV-C binding and replication." (PMID 28472984, 2017). "Finally, CDHR3, encoding a cell adhesion protein is linked to childhood asthma and rhinovirus-C susceptibility, was also located in a region under selection in Asian sheep by HapFLK." (PMID 34220925, 2021). "eQTL also confirmed cadherin-related family member 3 (CDHR3) gene, as an epithelial susceptibly gene for severe exacerbations in childhood asthma." (PMID 27658857, 2016).
viral infections (5 papers, 2016 to 2023). "Rs6967330-G was the more modern missense mutant that selected out under the pressure of evolving RV-C species to protect the general population from this viral infection by encoding the defective CDHR3 protein and downregulating its surface expression." (PMID 37750685, 2023). "Recently, it was shown that CDHR3 is involved in binding of Rhinovirus C and mediated entering of rhinovirus C into the host cells, providing a model of epithelial susceptibility for viral infections." (PMID 27701444, 2016). "Collectively, scRNA-seq data analysis of the three cell culture models showed expression of CDHR3, CD55 and ACE2 receptors in ciliated, secretory and basal cells, suggesting the possibility of modeling ssRNA virus infection, including SARS-CoV-2, in the airway epithelium in vitro." (PMID 37569398, 2023).
breast carcinoma (2 papers, 2014 to 2023). "Gene expression analysis also suggested decreased expression of adhesion molecules such as cadherin-related family member 3, CD226, Claudin 7 and Ocludin, upon breast cancer cells exposure to LDL." (PMID 24428917, 2014).
allergic asthma (1 paper, 2025). A asthma with a basis in a pathological type I hypersensitivity reaction. "The effect of the CDHR3 variant may be more pronounced in patients with allergic asthma, because plasmacytoid dendritic cells in these individuals have a reduced ability to produce high levels of IFN-α/β in response to viruses." (PMID 40687950, 2025).
aspiration pneumonitis (1 paper, 2024). Inflammation of the lungs due to the inhalation of solid or liquid material. "The differential diagnosis for this case is as follows: severe persistent asthma with a possible link to genetic mutations such as CDHR3, hyper-IgE syndrome, atypical presentation of Wiskott-Aldrich syndrome, and severe gastroesophageal reflux disease (GERD) with aspiration pneumonitis." (PMID 38414706, 2024).
atopic asthma (1 paper, 2020). An asthma that is characterized by symptoms that are triggered by an allergic reaction caused by inhaled allergens such as dust mite allergen, pet dander, pollen and mold. "EGFR and cadherin-related family member 3 (CDHR3) protein expression was increased in airway epithelial cells from atopic asthma subjects compared to control subjects." (PMID 33217964, 2020).
bronchiolitis (1 paper, 2024). Inflammation of the bronchioles characterized by swelling of the bronchioles and mucus accumulation. "Our results indicate that the CDHR3 variant rs6967330-A increases susceptibility to acute viral bronchiolitis in general and particularly if the causative agent is other than RSV." (PMID 39299705, 2024). "The GWAS of bronchiolitis by any causative virus found 2 associated loci (P < 5 × 10−8), located within CDHR3 and GSDMB." (PMID 39299705, 2024). "We conducted colocalization analysis to assess if the bronchiolitis association in the CDHR3 or GSDMB locus could be mediated by gene expression." (PMID 39299705, 2024). "Thus, studying specific causative viruses of bronchiolitis and their interaction with CDHR3 in molecular biological studies could provide further insight into bronchiolitis pathobiology." (PMID 39299705, 2024). "We identified bronchiolitis-associated loci in gasdermin B (GSDMB) and cadherin-related family member 3 (CDHR3) by genome-wide association study." (PMID 39299705, 2024). "Our results suggest that genetic variants in CDHR3 and GSDMB modulate susceptibility to bronchiolitis, especially when caused by viruses other than RSV." (PMID 39299705, 2024). "We detected 2 loci, CDHR3 and GSDMB, that were associated with severe bronchiolitis in the GWAS." (PMID 39299705, 2024). "Variants suggested to be associated with rhinovirus-induced wheezing or non-RSV bronchiolitis include variants in a genomic region near 17q21 and cadherin-related family member 3 (CDHR3)." (PMID 39299705, 2024). "In summary, the current study provides evidence of genetic associations and perhaps genetically mediated functional mechanisms for the CDHR3 and GSDMB loci in severe bronchiolitis." (PMID 39299705, 2024). "In line with the known role of CDHR3 in rhinovirus pathophysiology, our results found a nominal association in the analysis of non-RSV bronchiolitis (P = 6e−3) but not in the analysis of RSV bronchiolitis (P = .29)." (PMID 39299705, 2024).
cholesteatoma (1 paper, 2019). A pathologic process characterized by the proliferation of keratinizing squamous epithelium resulting in the accumulation of keratin and cells in the middle ear and/or mastoid. "While the GWAS finding of CDHR3 variant rs114947103 as a protective factor against OM has not been replicated, the downregulation of CDHR3 in cholesteatoma compared to mucosal middle ear tissue (adj-p = 0.004) in our RNA-Seq study strongly supports a role for CDHR3 in OM." (PMID 32010199, 2019).
chronic lung disease (1 paper, 2022). According to the definitions of the American and British Thoracic Societies, including pulmonary functional tests, X-rays, and CT scans for items such as fibrosis, bronchiectasis, bullae, emphysema, nodular or lymphomatous abnormalities. "Further research is warranted to profile the cadherin-related family member 3 (CDHR3) receptor adhesion site for HRV-C in lung tissues from chronic lung diseases to devise further preventive anti-viral strategies." (PMID 35316427, 2022).
eosinophilia (1 paper, 2022). "Examples of pathways or networks that are implicated by GWASs in asthma are the IL33-IL1-RL1 receptor pathway, leading to eosinophilia, and the T-helper-2 (Th2) cytokine IL-5 and IL-4RA receptor, leading to eosinophilia and type 2 inflammation or viral response (CDHR3, ORMDL3)." (PMID 35656293, 2022).
Respiratory tract infection (1 paper, 2023). An infection of the upper or lower respiratory tract. "This case-control study investigated the interaction between CDHR3 genotypes and rhinovirus (RV) species on disease severity in Hong Kong children hospitalized for respiratory tract infection (RTI)." (PMID 37750685, 2023).
infection (11 papers, 2016 to 2026). The state of being infected such as from the introduction of a foreign agent such as serum, vaccine, antigenic substance or organism. "This SNP (rs6967330) results in a C529Y amino acid (aa) change in the CDHR3 protein, associated with increased expression at the cell surface upon transfection, favoring RV-Cs infection." (PMID 36937308, 2023). "GMDR analyses revealed epistatic interaction between rs140154310 and rs6967330 of CDHR3 for RV-C infection (P = 0.001), RV-C-associated lower RTI (P = 0.004), and RV-C-associated wheeze (P = 0.007)." (PMID 37750685, 2023). "Both 17q21 locus and CDHR3 are linked to differential susceptibility to infection by rhinoviruses, and our data suggest that such susceptibility is common and important for early-onset nontransient phenotypes (both persistent and intermittent)." (PMID 35050846, 2022). "The intracellular distribution of CDHR3 and the loss of protein expression after RV-C15 infection in HAE suggests CDHR3 follows the same path as other RV receptors." (PMID 34995322, 2022). "C15 infection caused a 27.4% reduction of ciliated cells expressing CDHR3 (p < 0.01)." (PMID 28472984, 2017). "The CDHR3 gene risk allele is associated with a ten-fold increase in cellular CDHR3 expression and has been shown to increase RV-C infection levels and protein surface localisation of the receptor on epithelial cells potentially leading to more severe infection." (PMID 34912343, 2021). "Conversely, infection induced the downregulation of CDHR3 and more significantly in asthmatic donors." (PMID 36937308, 2023). "To better understand the dynamics of FoxJ1, acetylated alpha-tubulin, and CDHR3 during infection, we analyzed global protein expression by Western blot (WB) and quantified fluorescence levels following immunostaining specifically in infected cells." (PMID 34995322, 2022). "The soluble recombinant CDHR3 protein panel was tested for its ability to inhibit C15 infection of stably transduced fCR3Y cells." (PMID 30532249, 2018). "Just like C15, C02, C41, and C45 infections were inhibited by soluble CDHR3 rEC1 and rEC1-3, in a dose dependent manner." (PMID 30532249, 2018). "Despite having similar 3D structures, some bind members of the low-density lipoprotein receptor family, some ICAM-1, and some use CDHR3 for host cell infection." (PMID 27251607, 2016). "This suggests that epithelial cell damaged due to infection may trigger the repair process, which in turn may lead to an increase of immature cells and increased CDHR3." (PMID 34912343, 2021). "Notably, since CDHR3—the receptor for RV‐C—is poorly expressed in immune cells, the detection of RV‐C RNA may reflect nonspecific uptake, infection of rare susceptible cells, or alternative entry mechanisms." (PMID 41578919, 2026). "Everman and colleagues found that CDHR3 knockdown affected RV-C binding but not replication and suggested that RV-Cs use a coreceptor for infection." (PMID 36937308, 2023). "In addition, by creating CDHR3 knockout AECs, they demonstrated that HRV-C infection was reduced by 80% in these cells, strongly supporting the role of CDHR3 as a receptor for HRV-C cellular infection." (PMID 33925009, 2021).
tumor (2 papers, 2020 to 2023). "In more detail, SIGLEC17P expression could be used by Tregs to circulate among all tissues; CD33, PCDH1, JAM2, CDHR3, and ITGA3 would orchestrate migration/retention in NI TDLNs; CADM1 in I TDLNS; and CEACAM6 in tumor." (PMID 32601304, 2020).
cancer (1 paper, 2015). A tumor composed of atypical neoplastic, often pleomorphic cells that invade other tissues. "We selected those genes with functions known to be associated with cancer of which there were 12—SNVs: NOTCH2, PIK3CG, IL2RB, BAI3, FREM2 and RERE; indels: UTRN, CDHR3, NCOA5, CABYR, HOTAIR and FOLH1." (PMID 26017033, 2015).
CDHR3 also shares sentences with these, for which no sentence is quoted: otitis media (2 papers); autism spectrum disorder (1); bipolar disorder (1); Childhood onset (1); depression (1); gastroesophageal reflux disease (1); herpes zoster (1); neurodegenerative disease (1); psychiatric disorder (1); RSV bronchiolitis (1); schizophrenia (1); type 2 diabetes (1); Wiskott-Aldrich syndrome (1).